LINC02454 (long independently transcribed non-coding RNA 2454)
Gene: Long non-coding RNA gene on chromosome 12 (65,589,095 to 65,622,806, forward strand). Ensembl gene ENSG00000256268.
Diseases named in the same sentence as LINC02454 in open-access papers:
LINC02454 is named in the same sentence as 7 diseases in open-access papers, as found by Europe PMC text mining. Sharing a sentence is not in itself a finding about the gene and the disease. The quoted sentences say what the papers report.
glioma (2 papers, 2024 to 2025). A benign or malignant brain and spinal cord tumor that arises from glial cells (astrocytes, oligodendrocytes, ependymal cells). "By contrast, the SORBS2 locus, which encodes a gene downregulated in LINC02454 KD glioma cells, showed significant interaction with the LINC02454 enhancer based on Capture-C data." (PMID 38177123, 2024). "Finally, ATAC-seq analysis indicated an open chromatin status of LINC02454-associated SE regions in glioma cells." (PMID 38177123, 2024). "LINC02454, transcribed from a glioma-specific super-enhancer, modulates two target genes with opposite effects on drug response." (PMID 41154382, 2025). "In our study, KEGG analysis shown that LINC02454 KD in glioma cells induced significant changes in MAPK signaling." (PMID 38177123, 2024). "An important finding reported here is that SORBS2 and DDR1 are two major genes regulated by LINC02454, and that both regulate glioma cell sensitivity to TMZ." (PMID 38177123, 2024). "To identify other genes regulated by LINC02454 that govern glioma cell sensitivity to TMZ, we analyzed RNA-seq data of LINC02454 KD and OE U251 glioma cells and U251 glioma cells treated with TMZ (50 μM) for 0, 4, 9,12, and 16 days." (PMID 38177123, 2024). "ChIP-seq data indicated H3K27ac enrichment at the LINC02454 locus in glioma cells, which was identified as the LINC02454 super-enhancer (LINC02454 SE)." (PMID 38177123, 2024). "Here, we show that the SE lncRNA LINC02454 has bivalent and opposing functions in regulating glioma cell TMZ sensitivity." (PMID 38177123, 2024). "By contrast, LINC02454 activity also decreased glioma cell TMZ sensitivity by promoting DDR1 expression." (PMID 38177123, 2024). "Among them, 11 were upregulated in LINC02454 KD glioma cells and downregulated in LINC02454 OE cells, while 21 were downregulated in LINC02454 KD glioma cells and upregulated in LINC02454 OE cells." (PMID 38177123, 2024). "KEGG analysis of LINC02454 KD glioma cells indicated that genes differentially expressed in LINC02454 KD relative to control cells were significantly enriched in cancer progression-associated signaling pathways like MAPK and Rap1." (PMID 38177123, 2024). "On one hand, LINC02454 activity enhanced SORBS2 expression by maintaining 3D chromatin interactions via the LINC02454 SE, increasing glioma cell sensitivity to TMZ." (PMID 38177123, 2024). "Our study suggests a bivalent function for super-enhancer RNA LINC02454 in regulating glioma cell sensitivity to TMZ." (PMID 38177123, 2024). "In this study, we identified a SE-derived long non-coding RNA, LINC02454, that regulates glioma TMZ sensitivity through maintenance of 3D chromatin structure." (PMID 38177123, 2024). "Knock-out of the LINC02454 SE in glioma cells downregulates LINC02454 levels." (PMID 38177123, 2024). "RNA-seq analysis of LINC02454 KD and OE glioma cells revealed global changes in mRNA levels." (PMID 38177123, 2024). "Overall, these results suggest that LINC02454 functions in glioma cell sensitivity to TMZ." (PMID 38177123, 2024). "On one hand, LINC02454 maintains a long-range enhancer–promoter loop that upregulates SORBS2, a gene whose expression was found to increase TMZ sensitivity in glioma cells." (PMID 41154382, 2025). "Our findings suggest that SE activity at the LINC02454 locus increases glioma cell sensitivity to TMZ by regulating expression of SORBS2 (Sorbin and SH3 domain containing 2) via long-range chromatin interactions, and that LINC02454 maintains this chromatin loop." (PMID 38177123, 2024). "However, LINC02454 KD in glioma cells increased TMZ sensitivity, an outcome opposite to the decrease in TMZ sensitivity seen in LINC02454 SE KO glioma cells." (PMID 38177123, 2024). "ChIRP-qPCR results also showed significant enrichment of LINC02454 at the DDR1 locus in control but not LINC02454 KD glioma cells, suggesting that LINC02454 binds to that locus and regulates DDR1 transcription." (PMID 38177123, 2024).
glioma (continued). "We found that LINC02454 KD downregulated DDR1 transcription and increased glioma cell TMZ sensitivity, consistent with a previous study of GBM showing that inhibition of DDR1 combined with radiochemotherapy including TMZ increased TMZ sensitivity and prolonged patient survival." (PMID 38177123, 2024). "In conclusion, our study shows that LINC02454 increases glioma cell TMZ sensitivity by maintaining chromatin interactions between the SORBS2 gene and a LINC02454 enhancer and at the same time can decrease TMZ sensitivity of glioma cells by promoting DDR1 expression." (PMID 38177123, 2024). "Thus, LINC02454 may regulate DDR1 and alter glioma cell TMZ sensitivity through the MAPK pathway, although further studies are required for confirmation." (PMID 38177123, 2024). "Although other lncRNAs have been reported to function in glioma TMZ sensitivity, our study reveals a new mechanism by which LINC02454 and a corresponding SE co-regulate glioma sensitivity to TMZ by altering 3D chromatin structure and through bivalent LINC02454 activities." (PMID 38177123, 2024).
thyroid cancer (2 papers, 2024). "To investigate the role of LINC02454 in thyroid cancer tumorigenesis, we constructed coexpression gene network for turquoise module." (PMID 39218967, 2024). "Thus, in the present study, we sought to further explore how the key LINC02454-related pathways and key genes are involved in thyroid cancer oncogenesis by weighted gene coexpression network analysis (WGCNA)." (PMID 39218967, 2024).
thyroid (1 paper, 2024). "Moreover, IL1RAP seemed to be coexpressed with LINC02454 and activated the MAPK pathway in thyroid tumorigenesis." (PMID 39218967, 2024).
cancer (4 papers, 2021 to 2024). A tumor composed of atypical neoplastic, often pleomorphic cells that invade other tissues. "Second, further analysis has identified seven NET-related genes, including NIFK, LINC00460, NUTF2, and LINC02454, some of which are potentially predictive biomarkers for human cancers." (PMID 36225931, 2022). "Some of the irlncRNAs previously associated with the malignant phenotypes of various cancers, including MIAT, TYMSOS, LINC01063, HOXC-AS1, LINC02454, SCAT1, and LINC01322 were identified in the process of modeling in this study." (PMID 34167440, 2021).
LINC02454 also shares sentences with these, for which no sentence is quoted: papillary thyroid cancer (2 papers); tumor (2); lymph node metastasis (1).